CD200 (CD200 molecule)
Diseases named in the same sentence as CD200 in open-access papers (continued):
Sharing a sentence is not in itself a finding about the gene and the disease.
tumor (continued). "Furthermore, CD200 can affect EMT gene expression and tumour regulation by binding to β-catenin and translocating it into the nucleus." (PMID 40181975, 2025). "CD200 functions as an immunosuppressive molecule through its receptor CD200R, and its upregulation in BC may facilitate immune escape and contribute to tumor progression and metastasis." (PMID 40666524, 2025). "Furthermore, significant differences in the expression of immune checkpoints—specifically CD200, CD274 (PD-L1), TIGIT, TNFRSF25, and TNFSF15—were observed between tumor and normal samples." (PMID 40666524, 2025). "The CD200/CD200R1 axis has been shown to be involved in the expansion of the MDSC population and tumor proliferation, and different studies have suggested that inhibition of this axis could enhance the efficacy of immunotherapy." (PMID 40904466, 2025). "Here, we integrated and refined TCGA sourced tumor-related DEGs with genes from TISIDB related to immune to ultimately establish a four-gene prognostic signature comprising CD276, MS4A1, IGFBP1 and CD200, which has the ability to reflect ICIs responses and survival outcomes." (PMID 41488652, 2025). "CD200 is a cell surface glycoprotein that binds to its receptor, CD200R, primarily expressed on myeloid and lymphoid cells and, in case of malignancies, also on tumor cells." (PMID 40075669, 2025). "These may be dictated by certain genetic mutations or gene variations that could affect the expression of both CD200 and its receptor, CD200R, on the tumor and immune cells." (PMID 39795972, 2024). "We hypothesized that CD200 is overexpressed on tumor and stromal populations in the pancreatic TME and that circulating levels of soluble CD200 (sCD200) have prognostic value for overall survival." (PMID 38619621, 2024). "In the Merkel cell tumor xenograft model, high CD200 mRNA expression was found in MCC tumors, and CD200 immunostaining was demonstrated on >95% of MCC tumors, with CD200R+ myeloid cells present in the MCC tumor microenvironment." (PMID 38540350, 2024). "All the dogs in this study were treated with a combination of autologous tumor lysate (ATL) and a peptide ligand that interferes with the CD200 immune checkpoint, yet there was a marked disparity in survival time between French bulldogs and boxers and Boston terriers." (PMID 39794971, 2024). "Finally, this group reported that anti-CD200 therapy was ineffective alone, or in combination with checkpoint inhibitors, including anti-PD-1 and anti-CTLA4, in inhibiting Yumm1.7 tumor growth." (PMID 38540350, 2024). "CD200, a membrane protein with immunosuppressive function expressed in hematopoietic tumors, suppresses the body's antitumor immunity by binding to the receptor CD200R, inducing Treg expression, and inhibiting tumor‐specific T‐cell function." (PMID 39224537, 2024). "Thus, an immune checkpoint inhibitor (ICI) to block the immunosuppressive effect of CD200 was developed and used in conjunction with ATL therapy in the dogs presented herein, following surgical tumor resection." (PMID 39794971, 2024). "Among these, CD273 and CD146 may indeed be MSC-specific, whereas CD36 (a receptor for thrombospondin-1), CD200 (also expressed on tumor cells), CD274 (PDL-1), and CD248 (endosialin) are also expressed in fibroblasts, often in a tumor context." (PMID 39201399, 2024). "The results showed that CD200, CD80 and TNFRSF14 were the highest in tumor tissues, CD274 (PDL1), CD86, LGALS9, NECTIN2, PDL2, PVR were lower than those in adjacent tissues but higher than those in normal tissues, and FGL1 was the lowest in tumor tissues." (PMID 39120585, 2024). "Similarly, the CD200/CD200R axis has also been documented to suppress the adaptive immune response by inhibiting effector and memory T cell anti-tumor activity." (PMID 38137547, 2023).
tumor (continued). "Similar to other immune checkpoint proteins, such as cytotoxic T lymphocyte antigen 4 (CTLA-4) and program death-1 (PD-1), CD200 is thought to play a pro-tumorigenic role, via engagement of CD200R, in many tumor types primarily by suppressing anti-tumor T-cell and natural killer cell responses." (PMID 36738455, 2023). "And CD200 (OX-2), on the other hand, is a cell surface glycoprotein that confers immune escape by suppressing the alloimmune and autoimmune responses through its receptor CD200R.B7-H3 (CD276) is overexpressed in a variety of tumor types." (PMID 36923439, 2023). "Overall, through these findings and those of additional experiments, this study effectively demonstrated that CD200 in the BCC TME suppresses NK cells’ cytotoxic activity and induces NK cell apoptosis, which foster immunosuppressed conditions favoring tumor development." (PMID 36756156, 2023). "CD200 overexpression in AML can directly suppress anti-tumor NK cell and memory T cell functions, and the suppression of pro-inflammatory cytokines by CD4+ Th1 cells and CD8+ memory T cell numbers in AML patients can be restored with anti-CD200 treatment." (PMID 36738455, 2023). "Third, there appears to be little to no overlap in the putative molecular regulators of CD200 expression across different tumor types." (PMID 36738455, 2023). "Interestingly, these studies have demonstrated a synergistic role of CD200 and/or CD200R in amplifying the anti-tumor effects of these therapies." (PMID 38137547, 2023). "Therefore, the interactions between CD200 and CD200R in the TME negatively modulate levels of immune activity, ultimately fostering an environment that favors tumor development, growth, and spread." (PMID 36756156, 2023). "However, other studies indicated that CD200/CD200R engagement can lead to the expansion of MDSCs, which is tumour-promoting." (PMID 37082107, 2023). "These secondary CCL8 effects are additional mechanisms believed to drive tumor growth in the absence of CD200/CD200R signaling." (PMID 38137547, 2023). "We showed that CD200 and CD200R are expressed on both tumor and stromal cells of NSCLC patients." (PMID 33804482, 2021). "Tumor CD200 expression did not significantly predict disease-free survival (DFS) (p = 0.84) after surgery or overall survival (OS) (p = 0.55) in early-stage NSCLC patients." (PMID 33804482, 2021). "CD200 expression was heterogeneous in tumor and stromal cells and did not demonstrate prognostic value in this cohort." (PMID 34771664, 2021). "Neither anti-CD200 or anti-PD-1 monotherapy, nor their combination showed any efficacy, as measured by tumor growth kinetics, AUC or tumor weight at the end of the experiment." (PMID 34692697, 2021). "Previous reports on the expression of CD200/CD200R on tumor-infiltrating immune cells in NSCLC are lacking." (PMID 33918618, 2021). "CD200 interacts with its receptor CD200R1 to trigger immunosuppressive signals, resulting in macrophage suppression, regulatory T cell induction, cytokine profile switching from Th1 to Th2, and finally the inhibition tumor-specific T-cell immunity." (PMID 34136486, 2021). "In fact, both the membrane and soluble forms of CD200 can engage the CD200 receptor, which in turn can result in increased tumor growth, by means of a negative impact on tumor immunosurveillance." (PMID 34439393, 2021). "CD200 exhibited a rather heterogeneous pattern of expression, with areas staining positive and others staining negative even within the same tumor." (PMID 33804482, 2021). "Our results demonstrate the potential utility of activating CD8 cell infiltration in the tumor microenvironment of PDAC, inhibiting FAP and its mechanisms, and blockade of CD200, as well as the potential of each of these proteins in companion diagnostics tests for immunotherapy treatments." (PMID 34771664, 2021).
tumor (continued). "Notably, some genes related to exhaustion were also overexpressed in tumor‐infiltrating Tregs including TYMS, KIAA0101, CXCL13, CD27, HLA‐DQB1, HLA‐DMA, ENTPD1, CD200, DUSP4, and ZBED2." (PMID 32659053, 2020). "Blockade of the CD200-CD200R immune checkpoint using a therapeutic anti-CD200 mAb was hypothesized to restore and/or enhance tumor cell recognition and CTL mediated anti-tumor responses in advanced CLL and MM patients with limited therapeutic options." (PMID 31443741, 2019). "In another study, the CD200/CD200R axis was shown to induce tolerance to external and tumor antigens and to influence the ratio of Treg/Th17 cells and control the balance of Treg/T effector cells, which provides a therapeutic strategy for CD200 blocking antibodies." (PMID 31775797, 2019). "Treatment with agonistic anti-CD200R did not inhibit tumor growth in several tumor models in mice with endogenous expression of CD200, indicating that further CD200R stimulation does not affect tumor growth." (PMID 30653571, 2019). "As monotherapies with SMO antagonists (e.g., vismodegib) inhibiting the Hedgehog pathway are not curative, the authors suggest to target the CD200+ cells instead for a permanent elimination of the tumor." (PMID 29896477, 2018). "If CD200-positive CAFs augment the effect of gefitinib, one would expect the PFS of the patients possessing CD200-positive CAFs in the microenvironment of the tumor to be elongated after treatment." (PMID 28429795, 2017). "Our data show an important correlation with augmented CD8+ cytotoxic T cells and resistance to tumor growth in mice lacking exposure (on either host cells or tumor) to the immunoregulatory molecule CD200." (PMID 28234914, 2017). "It should be noted that in the absence of additional immunotherapy as used in these studies, use of metformin alone in either WT or CD200-/- mice receiving EMT6 tumors did not lead to any significant attenuation of tumor growth (RMG-unpublished)." (PMID 28234914, 2017). "However, depending on the context, it is also possible that CD200 inhibits CLL progression by dampening inflammation, which is thought to promote tumor progression in many cancers." (PMID 26910908, 2016). "Furthermore, CD200 expression on CLL has been engaged in the induction of regulatory T cells, suggesting that CD200 blockade may promote antigen specific-T cell response through suppression of regulatory T cells, which have an immune suppressive role in the initiation and progression of neoplasms." (PMID 26910908, 2016). "In addition to this, RT-qPCR of CD200 and STAG3 was carried out on the whole tumor RNA samples used for the RNA-Seq (n=8 HPV(+) and n=8 HPV(−)." (PMID 27462861, 2016). "Lack of CD200R signaling inhibits outgrowth of an endogenous tumour irrespective of CD200 expression by the tumour cells." (PMID 27212807, 2016). "In the EMT6 model, increased immunosuppression and attenuation of an inflammatory response (by increased signaling through CD200:CD200R1 in CD200tg mice, or with CD200tg tumor cells 13) led to increased metastasis, while the reverse was the case in CD200R1KO mice." (PMID 26725371, 2016). "The current studies have extended our understanding of host resistance to EMT6 tumors using WT mice as tumor recipients, and, following surgical resection of tumor, by augmenting immunization with tumor cells (with CpG as adjuvant) with infusion of Fab anti-CD200R to block CD200:CD200R interactions." (PMID 25409195, 2014). "In in vitro cultures, CD200-positive tumor cells but not CD200-negative tumor cells strongly suppress cytokine production by myeloid cells." (PMID 22319630, 2012). "In parallel, a third group of mice received B16.OVA.CD200 tumor cells i.v. at a dose of 1×105/mouse without mAb treatment." (PMID 22319630, 2012). "The CD200:CD200R1 interaction could modulate the TME, accelerating tumor growth and metastasis." (PMID 40936767, 2025).
tumor (continued). "Interactions between the circulating CD200 + myeloid cells and CD200R + MDSCs could be promoting the differentiation and expansion of immunosuppressive myeloid populations that could infiltrate into the tumor and promote an immunosuppressive TME." (PMID 38619621, 2024). "These authors, at least, concluded that the blockade of endogenous CD200 can prevent the tumorigenic effect of CD200R-expressing myeloid cells in the tumor microenvironment, but agonistic anti-CD200R may not necessarily produce such an effect." (PMID 38540350, 2024). "CD200 expressed in the tumor cell surface interacts with CD200R present in the membrane of various immune cells, and this molecular interaction provides an immune status capable of allowing tumor development and metastasis, while protecting the cancer cells from immune damage." (PMID 39795972, 2024). "In addition, in the tumor microenvironment, we found that PPRC1 expression in LIHC and OV had the same trend as some immune-cell molecular markers such as CD200, CD200R1, and LAIR1, although, in SKCM we found that PPRC1 expression had the opposite trend to that of some immune cell molecular markers." (PMID 37109742, 2023). "In an in vitro study, blockade of CD200 expression in CLL (by anti-CD200 antibody or siRNAs) decreased the number of CD4+CD25+Foxp3+Treg, enhanced production of the proinflammatory cytokines IFN-γ and TNFα by effector PBMCs, and augmented effective killing of tumor cells by CD8+ CTL." (PMID 33562512, 2021). "To determine if tumor CD200 interacts with CD200R on macrophages to regulate CCL8 production, we generated bone marrow derived macrophages (BMDM) from CD200R–/– and WT mice, co-cultured them with Yumm1.7 tumor cells and measured CCL8 gene expression and protein secretion." (PMID 34692697, 2021). "Hence, tumor growth could be inhibited by blockade of CD200–CD200R interaction, lending support to the idea that antagonistic CD200 or CD200R antibodies are an option in cancer treatment." (PMID 32117298, 2020). "These authors firstly demonstrated that human peripheral blood mononuclear cells (hPBMCs) and Namalwa tumor cells (Burkitt’s lymphoma cell line lacking CD200 expression) simultaneously injected in NOD/SCID mice show reduced tumor growth with respect to that observed in mice in the absence of hPBMCs." (PMID 33324560, 2020). "Accumulated evidence supports the rationale for developing therapeutic anti-CD200 antibodies lacking effector function to block CD200-CD200R-mediated signaling while preserving immune components critical for anti-tumor immunity such as activated T cells and dendritic cells." (PMID 31443741, 2019). "In addition, we previously showed that the absence of CD200R signaling pathway inhibits the growth of endogenous cancer cells even without CD200 expression in the tumor cells." (PMID 30653571, 2019). "The combination of metformin with immunotherapy, and lack of CD200 expression in either tumor (EMT6siCD200 tumors in WT mice) or host (CD200-/- mice) resulted in increased survival and prevention of lung metastasis compared with either immunotherapy or metformin treatment alone." (PMID 28234914, 2017). "More detailed analysis of tumor growth in these mice showed that while EMT6siCD200 tumors were smaller than control EMT6 tumors, they had a greater percentage of CD45+ infiltrating immune cells, suggesting an enhanced immune response in hosts bearing tumors with reduced CD200 expression." (PMID 28234914, 2017). "The studies below compared protection seen in surgically treated/immunized EMT6 or 4THM tumor injected WT mice with/without manipulation of CD200:CD200R interactions using Fab anti-CD200R, with attenuation of disease after surgical resection followed by chemotherapy." (PMID 25409195, 2014).
tumor (continued). "High levels of CD200 have been associated with poor prognosis in certain cancers, suggesting that CD200 may be protecting the tumor by inhibiting myeloid cells through CD200R, and CD200 mAb are being tested to restore myeloid cell activity and help eliminate tumor cells." (PMID 23602662, 2013). "Many CD markers are by no means exclusive to certain stages or lineages, and it should be noted that CD200 is promiscuously expressed in a number of tissues including neural tissue, mesenchymal cells and tumor lines and also immature pluripotent stem cells (not shown)." (PMID 23826393, 2013). "In addition, a soluble form of CD200 (sCD200), released following CD200 ectodomain shedding by matrix metalloproteinase-1 (MMP1) and ADAM19 metallopeptidase, is able to engage CD200R1, can be quantified in the serum, and has been correlated with worse tumor prognosis in CLL and GBM patients." (PMID 40904466, 2025). "Our observation that CD200 expression increases on myeloid populations coupled with previous observations of myeloid populations (macrophages and MDSCs) being abundant in PDAC may suggest that CD200 is promoting tumor progression through a myeloid-dependent mechanism." (PMID 38619621, 2024). "While targeting of CD200, TIGIT, and LAG3 is less established in GBM treatment, these targets should be highly considered for future drug development as they appear to be present in GBM and may serve as a strong alternative target should a patient’s tumor express low amounts of PD-1/PD-L1 or CTLA4." (PMID 39409893, 2024). "Likewise, a monoclonal antibody that targets CD200 and prevents the ligand from binding to CD200R may effectively block the protein’s immunosuppressive signaling and restore the body’s protective defenses against tumor growth." (PMID 36756156, 2023). "Importantly, we report novel data on immune cell expression of the newly described CD200/CD200R1 pathway, and the leukocyte immunoglobulin-like receptors (LILRs), which may represent novel innate immune checkpoints, dampening the anti-tumor T cell immune response in NSCLC." (PMID 33918618, 2021). "We report characterization of tumor infiltrating (TILs) and draining lymph node (DLN) cells in WT and CD200-/- BALB/c mice, receiving WT tumor cells, or EMT6 lacking CD200 expression (EMT6siCD200 cells)." (PMID 28234914, 2017). "to characterize tumor infiltrating lymphocytes (TILs) and draining lymph node (DLN) cells in WT and CD200-/- BALB/c mice, receiving WT tumor cells, or EMT6 lacking CD200 expression (EMT6siCD200 cells)." (PMID 28234914, 2017). "While the immunosuppressive and tumor-promoting effects of CD200/CD200R are well documented, evidence suggests this pathway may not always favor tumor progression." (PMID 40075669, 2025). "CD200 was found to be heterogeneously expressed in both the tumor and stromal compartments of PDAC, with the majority of patients having positive stromal expression and negative tumor expression." (PMID 34771664, 2021). "CD200/CD200R is not expressed on 4THM tumors, and thus an immune response to such tumor-bearing epitopes could not explain the differences observed above." (PMID 25409195, 2014). "Thus, triggering CD200R inhibits tumor foci formation in the lungs and targeting CD200R by a triggering mAb is feasible for the treatment of CD200-negative tumors." (PMID 22319630, 2012).